CRB1 (crumbs cell polarity complex component 1)
Description:
Plays a role in photoreceptor morphogenesis in the retina (By similarity). May maintain cell polarization and adhesion (By similarity).
Synonyms: LCA8; CRB1-A; CRB1-B; CRB1-C; RP12
Tractability: Small molecule: a structure with a bound ligand is known. Antibody: UniProt places it where antibodies can reach, with high confidence; UniProt predicts a signal peptide or a membrane-spanning region; its Gene Ontology location is reachable by antibodies, with medium confidence.
Gene: Protein-coding gene on chromosome 1 (197,268,204 to 197,478,455, forward strand). Ensembl gene ENSG00000134376.
Subcellular location: Apical cell membrane (Isoform 1); Secreted; Cell projection, cilium, photoreceptor outer segment; Photoreceptor inner segment; Secreted (Isoform 2)
Subcellular location (Human Protein Atlas): Vesicles; Predicted to be secreted
Gene Ontology:
Molecular function: protein binding; calcium ion binding
Biological process: cell-cell signaling; establishment or maintenance of cell polarity; establishment or maintenance of epithelial cell apical/basal polarity; heterophilic cell-cell adhesion; cell communication; retina morphogenesis in camera-type eye; signaling
Cellular component: adherens junction; protein-containing complex; apical junction complex; apical plasma membrane; photoreceptor inner segment; plasma membrane; apical part of cell; extracellular region; glial cell projection; microvillus; photoreceptor outer segment; subapical complex
Genetic constraint (gnomAD): Loss-of-function variants: 80 observed, 124.12 expected, observed/expected ratio (o/e) 0.64, 90% interval 0.54 to 0.78. The upper end of that interval is the gene's LOEUF score, 0.78, which puts it in group 3 of 6, group 1 being the genes least tolerant of losing a copy. Missense variants: 1,670 observed, 1,742.7 expected, observed/expected ratio (o/e) 0.96, 90% interval 0.92 to 1. Synonymous variants: 610 observed, 636.79 expected, observed/expected ratio (o/e) 0.96, 90% interval 0.9 to 1.02.
Gene-disease validity (ClinGen):
ClinGen rates the evidence that CRB1 causes each of these diseases.
inherited retinal dystrophy (autosomal recessive): Definitive. An instance of retinal degeneration that is caused by an inherited modification of the individual's genome.
Homologues: Orthologues: chimpanzee CRB1 (99% identical), macaque CRB1 (96% identical), dog CRB1 (82% identical), rabbit CRB1 (79% identical), mouse Crb1 (76% identical), rat Crb1 (75% identical), pig CRB1 (74% identical), tropical clawed frog crb1 (47% identical), zebrafish crb1 (43% identical), Caenorhabditis elegans crb-1 (27% identical), Caenorhabditis elegans clec-78 (23% identical), Drosophila melanogaster uif (23% identical), and 4 more.
Diseases named in the same sentence as CRB1 in open-access papers:
CRB1 is named in the same sentence as 82 diseases in open-access papers, as found by Europe PMC text mining. Sharing a sentence is not in itself a finding about the gene and the disease. The quoted sentences say what the papers report.
Leber congenital amaurosis (67 papers, 2008 to 2026). Leber congenital amaurosis (LCA) is a retinal dystrophy defined by blindness and responses to electrophysiological stimulation (Ganzfeld electroretinogram (ERG)) below threshold, associated with severe visual impairment within the first year of life. "Pathogenic variants in Crumbs homolog 1 (CRB1) cause a wide range of severe ocular diseases, most commonly Leber congenital amaurosis and other forms of adult-onset macular dystrophy that lead to vision loss." (PMID 41373703, 2025). "Depending on the level of residual CRB1 activity and the genetic background, CRB1 mutations can cause severe congenital and early-onset retinal dystrophies, including Leber congenital amaurosis, retinitis pigmentosa, and cone–rod dystrophies." (PMID 38790254, 2024). "Crumbs homolog 1 (CRB1) is one of the key genes linked to retinitis pigmentosa and Leber congenital amaurosis, which are characterized by a high clinical heterogeneity." (PMID 38570189, 2024). "Mutations in the Crumbs homolog 1 (CRB1) gene cause autosomal-recessive retinitis pigmentosa (RP) and Leber congenital amaurosis, which are among the leading causes of inherited blindness." (PMID 38570189, 2024). "Inherited retinal dystrophies such as retinitis pigmentosa (RP) or Leber congenital amaurosis (LCA) can be caused by mutations in the CRB1 gene." (PMID 37886604, 2023). "The majority of patients with mutations in CRB1 develop either early-onset retinitis pigmentosa as young children or Leber congenital amaurosis as newborns." (PMID 37886604, 2023). "CRB1 gene mutations can cause early- or late-onset retinitis pigmentosa, Leber congenital amaurosis, or maculopathy." (PMID 37541258, 2023). "Retinitis pigmentosa and Leber congenital amaurosis are inherited retinal dystrophies that can be caused by mutations in the Crumbs homolog 1 (CRB1) gene." (PMID 37084726, 2023). "Crb1 is predominantly expressed in retinal cells and loss or mutation of Crb1 causes various retinal defects in human and mice, including Leber congenital amaurosis and retinitis pigmentosa." (PMID 35247383, 2022). "Mutations in the Crumbs homologue 1 (CRB1) gene cause inherited retinal dystrophies, such as early-onset retinitis pigmentosa and Leber congenital amaurosis." (PMID 33808129, 2021). "Mutations in CRB1 can cause a spectrum of inherited retinal dystrophies (IRDs), including RP and Leber Congenital Amaurosis (LCA)." (PMID 33673358, 2021). "Pathogenic variants in CRB1 lead to diverse recessive retinal disorders from severe Leber congenital amaurosis to isolated macular dystrophy." (PMID 34884448, 2021). "And mutation of CRB1 is correlated with a severe form of retinitis pigmentosa and with Leber congenital amaurosis." (PMID 32596394, 2020). "CRB1 is a major causal gene for inherited retinal degenerative diseases, including Leber’s congenital amaurosis, retinitis pigmentosa, and macular dystrophy." (PMID 32620864, 2020). "Leber congenital amaurosis (LCA) is an early-onset disease leading to blindness from near birth with CRB1 mutations accounting for 7–17% of cases and affecting approximately 10,000 patients worldwide." (PMID 31795518, 2019). "To date, over 150 disease-associated variants in CRB1 have been described, resulting in a range of retinal disease phenotypes including Leber congenital amaurosis and retinitis pigmentosa." (PMID 29391521, 2018). "In children, mutations in the CRB1 gene have been identified as a causal factor underlying Leber's congenital amaurosis (LCA) and early-onset retinitis pigmentosa (RP)." (PMID 28424578, 2017). "This is the first report of the occurrence of coat’s like vasculopathy in a patient diagnosed with Leber congenital amaurosis caused by a CRB1 mutation." (PMID 26872607, 2016). "In this unique case we are reporting the incidence of coat’s like vasculopathy in a patient diagnosed with Leber congenital amaurosis caused by CRB1 gene mutation, and its management." (PMID 26872607, 2016).
Leber congenital amaurosis (continued). "CRB1 mutations are associated with a series of autosomal recessive retinal dysthrophies such as Leber congenital amaurosis (LCA), early onset RP, and preserved para-arteriolar retinal pigment epithelium." (PMID 27806333, 2016). "Here, we report that ablation of Crb1 and Crb2 genes results in severe impairment of retinal function, abnormal lamination and thickening of the retina mimicking human Leber congenital amaurosis due to loss of CRB1 function." (PMID 24339791, 2013). "In humans, mutations in the CRB1 gene are responsible for retinal diseases such as Leber congenital amaurosis and retinitis pigmentosa." (PMID 24324803, 2013). "Mutations in the human CRB1 gene lead to one of the most severe forms of retinal dystrophies, called Leber congenital amaurosis." (PMID 24339791, 2013). "In humans, the Crumbs homologue-1 (CRB1) gene is mutated in progressive types of autosomal recessive retinitis pigmentosa and Leber congenital amaurosis." (PMID 24324803, 2013). "These mice display severe impairment of retinal function, abnormal lamination and thickening of the retina mimicking human Leber congenital amaurosis due to loss of CRB1 function." (PMID 24339791, 2013). "Mutations in CRB1 have been associated with a wide array of retinal dystrophies, including retinitis pigmentosa and Leber congenital amaurosis." (PMID 22863181, 2012). "CRB1 (Crumbs Cell Polarity Complex Component 1) mutations, associated with both RP and Leber congenital amaurosis, and ABCA4 (ATP Binding Cassette Subfamily A Member 4) mutations, typically associated with Stargardt disease but also capable of causing RP phenotypes, were also identified." (PMID 41562913, 2026). "Biallelic pathogenic variants in the CRB1 gene are associated with severe retinal dystrophies, including early onset severe retinal dystrophy/Leber congenital amaurosis (EOSRD/LCA), retinitis pigmentosa (RP), cone–rod dystrophy (CORD), and macular dystrophy (MD)." (PMID 40243434, 2025). "However, it should be noted that CRB1 variants been described in association with Coats-like exudative vasculopathy both in Leber congenital amaurosis and retinitis pigmentosa." (PMID 36769743, 2023). "Pathogenic variants in CRB1 lead to a huge variety of phenotypes ranging from milder forms of inherited retinal dystrophy, such as retinitis pigmentosa to more severe phenotypes such as Leber congenital amaurosis." (PMID 28819299, 2017). "Recently, CRB1 mutations were found to be associated with keratoconus in patients with Leber Congenital Amaurosis; in this case the authors suggested that the CRB1 mutations could make patients more susceptible to developing keratoconus." (PMID 19956409, 2009). "Case 6a illustrates that a severe, early-onset ABCA4-RD can occasionally mimic Leber congenital amaurosis (LCA), and in this case particularly with LCA caused by CRB1 variants." (PMID 38066771, 2023). "Retinitis pigmentosa (RP) and Leber congenital amaurosis (LCA) are inherited retinal dystrophies caused by mutations in, among others, the Crumbs homolog 1 (CRB1) gene." (PMID 37084726, 2023). "Mutations in the CRB1 gene are responsible for retinal diseases such as retinitis pigmentosa (RP), Leber congenital amaurosis (LCA), and macular dystrophy." (PMID 37541258, 2023). "Mutations in the Crumbs homolog-1 (CRB1) gene are associated with a variety of retinal degenerations including Leber congenital amaurosis (LCA) and retinitis pigmentosa (RP)." (PMID 38983543, 2022). "Mutations in the Crumbs homolog 1 (CRB1) gene cause both autosomal recessive retinitis pigmentosa (RP) and Leber congenital amaurosis (LCA)." (PMID 34946856, 2021). "Variations in the CRB1 gene are associated with a wide variety of autosomal recessive retinal dystrophies, including retinitis pigmentosa (RP), Leber congenital amaurosis (LCA), cone-rod dystrophy, isolated macular dystrophy, and foveal retinoschisis." (PMID 31438467, 2019).
Leber congenital amaurosis (continued). "In humans, mutations in the CRB1 gene can cause significant visual impairment, leading to a severe phenotype of retinitis pigmentosa (RP) and Leber congenital amaurosis (LCA)." (PMID 28671996, 2017). "Mutations in the human CRB1 gene cause autosomal-recessive progressive retinitis pigmentosa and Leber congenital amaurosis (LCA)." (PMID 24339791, 2013). "Mutations in crumbs homolog 1 (CRB1) have been shown to result in retinitis pigmentosa and Leber congenital amaurosis (LCA), a severe form of retinal dystrophy, present at birth." (PMID 23592920, 2013). "In human, Mpdz/Mupp1 is known to interact with CRB1, mutations in which cause recessively inherited human RP and Leber congenital amaurosis (LCA)." (PMID 20069063, 2010). "Mutations in Crumbs cell polarity complex 1 (CRB1) gene cause several types of IRD and, in Spain, represent the most frequent pathogenic variants among patients with Leber congenital amaurosis (LCA)." (PMID 41373703, 2025). "Retinitis pigmentosa (RP) and Leber congenital amaurosis (LCA) may stem from mutations in the Crumbs homolog 1 (CRB1) gene." (PMID 39451224, 2024). "For example, leber congenital amaurosis (LCA) is an inherited retinal degenerative disease caused by mutations in different genes, including CEP290, GUCY2D, CRB1, and RPE65." (PMID 36556333, 2022). "To study the effectiveness of gene perturbations in HF-iCas9 stem cells, we targeted several genes linked to Leber congenital amaurosis (LCA), a rare childhood-onset retinal dystrophy caused by mutations in the AIPL1, CRB1, and RPGRIP1 genes, among others." (PMID 36553630, 2022). "Among these are retinitis pigmentosa 12 (RP12) and Leber congenital amaurosis (LCA), severe ocular dystrophies leading to PRC degeneration caused by mutations in CRUMBS1 (CRB1) or CRB2." (PMID 31988089, 2020). "Variations in the Crumbs homolog-1 (CRB1) gene are associated with a wide variety of autosomal recessive retinal dystrophies, including early onset retinitis pigmentosa (RP) and Leber congenital amaurosis (LCA)." (PMID 31438467, 2019). "While mutations in human CRB1 are associated with early-onset retinitis pigmentosa (RP12) and Leber congenital amaurosis (LCA), it seems to be Crb2 in the mouse that has taken on this function." (PMID 28202468, 2017). "We describe in these CRB1 Leber congenital amaurosis mouse models the molecular and cellular events involving CRB proteins during the development of the retina." (PMID 24339791, 2013). "Mutations in AIPL1, CRB1, and CRX have been implicated in patients with Leber congenital amaurosis, rendering them susceptible to keratoconus." (PMID 19956409, 2009). "The current patient also manifested variants of unknown significance in CRB1 and ELOVL4, genes associated with Leber congenital amaurosis and autosomal dominant Stargardt macular degeneration, respectively." (PMID 40747364, 2025). "CRB1-associated retinal dystrophy is a rare inherited disease (IRD) characterized by variable phenotypic manifestations, ranging from retinitis pigmentosa and Leber congenital amaurosis to isolated macular dystrophies." (PMID 36769743, 2023). "Our proteomic data showed significant changes in the levels of proteins for retinitis pigmentosa (RPE65, RP2, MERTK, and RBP3), X-linked retinoschisis (RS1), CRB1-retinal dystrophy (CRB1), Usher syndrome (PCDH15), and Leber congenital amaurosis (RD3 and KCNJ13)." (PMID 36139394, 2022). "Biallelic pathogenic CRB1 variants have been linked to two severe, early-onset forms of retinal dystrophy: they have been found to cause 3–9% of autosomal recessive retinitis pigmentosa (RP) cases and 7–17% of autosomal recessive Leber congenital amaurosis (LCA)." (PMID 34946856, 2021). "Similarly, mutations in one of the three human orthologues, CRB1, result in Retinitis pigmentosa (RP12) and Leber congenital amaurosis, two of the most severe retinal dystrophies associated with blindness." (PMID 31834921, 2019).
Leber congenital amaurosis (continued). "CRB1 has been previously related to retinitis pigmentosa and Leber Congenital Amaurosis." (PMID 28800606, 2017). "Mutations in the apicobasal polarity gene CRB1 lead to diverse retinal diseases, such as Leber congenital amaurosis, cone-rod dystrophy, retinitis pigmentosa (with and without Coats-like vasculopathy), foveal retinoschisis, macular dystrophy, and pigmented paravenous chorioretinal atrophy." (PMID 35675330, 2022). "In Crb1 knockout mice (a model for Leber's congenital amaurosis), retinal vessels slipping through the outer nuclear layer towards the retinal pigment epithelium (RPE) due to the lack of adhesion in the subapical region of the photoreceptor inner segments could be well identified." (PMID 19838301, 2009). "Homozygous variants in human CRB1 result in autosomal recessive Leber congenital amaurosis (LCA) and retinitis pigmentosa (RP), with no established genotype–phenotype correlation." (PMID 36656098, 2023). "The most commonly reported is Leber congenital amaurosis (LCA) or early-onset severe retinal dystrophy (EOSRD), where CRB1 accounts for approximately 10% of all cases." (PMID 36099972, 2023). "CRB1 mutations are reported as cause of severe congenital and early-onset retinal dystrophies (EORD) with different phenotypic manifestations, including Leber congenital amaurosis (LCA), retinitis pigmentosa (RP) and cone-rod dystrophies." (PMID 23379534, 2013). "Mutations in the CRB1 gene (Crumbs homologue 1) have been linked to several human retinal dystrophies, including type 12 retinitis pigmentosa (RP12) and Leber congenital amaurosis (LCA)." (PMID 23226298, 2012). "Reduced levels of CRB2 in MGCs and/or photoreceptors or retinal progenitors in mice lacking CRB1 result in a significant more severe retinitis pigmentosa or Leber congenital amaurosis retinal phenotype." (PMID 33808129, 2021). "This study only included patients with rod-cone dystrophies or Leber congenital amaurosis (LCA) harboring specific culprit genes (DHDDS, CRB1, and CEP290) and at least 8 eyes that with BCVA measuring better or equivalent to 6/38." (PMID 40455038, 2025).